IL17A (interleukin 17A)
Diseases named in the same sentence as IL17A in open-access papers (continued):
Sharing a sentence is not in itself a finding about the gene and the disease.
autoimmune disease (1,314 papers, 2006 to 2026). A disorder resulting from loss of function or tissue destruction of an organ or multiple organs, arising from humoral or cellular immune responses of the individual to their own tissue constituents. "Previous studies have shown that variants within the IL17A locus are associated with elevated cytokine levels and increased severity of chronic periodontitis and autoimmune diseases." (PMID 41614937, 2026). "IL-17A, a pro-inflammatory cytokine, has been implicated in a variety of inflammatory and autoimmune diseases." (PMID 40867579, 2025). "This increase in systemic IL-17A levels, in turn, stimulates a pro-autoimmune response, increasing the risk of autoimmune disease development via endosomal Toll-like receptors." (PMID 40722611, 2025). "Overall, our findings align with previous reports showing limited IL-17A involvement in neurodegenerative conditions, contrasting with its well-established role in autoimmune diseases where sustained Th17 activation is a hallmark." (PMID 40150012, 2025). "T lymphocytes, producers of IL-17A, are also pathogenic cellular components of autoimmune diseases, such as multiple sclerosis or psoriasis." (PMID 40399383, 2025). "Given that IL-17A is implicated in other autoimmune disorders, acute lung injury, and lung fibrosis, it is plausible that it also contributes to the pathogenesis of CIP." (PMID 40963607, 2025). "The increased levels of IL-17A and IL-23 suggest the activation of the Th17 pathway, which is implicated in chronic inflammatory and autoimmune diseases." (PMID 39857734, 2025). "As IL-17A is highly linked to development of autoimmune disease, T cell production of IL-17A in response to both unmodified rmMPO and HA-rmMPO supports the assessed development of glomerulonephritis in mice receiving splenocytes from immunized mice." (PMID 40020049, 2025). "IL-17A is considered to increase the chemotactic activity of neutrophils and is associated with infectious and autoimmune diseases." (PMID 40093533, 2025). "While epidemiological and animal data remain promising, prenatal infection, autoimmune disease, or elevated maternal cytokines (especially IL-6 and IL-17a) increase offspring ASD risk." (PMID 41008370, 2025). "Consistent results suggest a pathogenic role for IL-17A in various mouse models of autoimmune disease." (PMID 40821838, 2025). "Although IL-17A and IL-17F have protective roles against certain infections, they are also key pathogenic cytokines in T cell-mediated autoimmune disease pathology." (PMID 40127923, 2025). "In autoimmune diseases, IL-17A seems to be often associated with another cytokine, a Th17 inducer, IL-23." (PMID 38638687, 2024). "The humanized IgG1 monoclonal antibody bimekizumab is designed to selectively target and suppress the pro-inflammatory cytokines IL-17A and IL-17F, both associated with autoimmune disorders." (PMID 38605952, 2024). "Our findings suggested that administering EBV DNA into mice increased systemic levels of the pro-inflammatory cytokine IL-17A, potentially acting as a risk factor for autoimmune disease." (PMID 38675965, 2024). "Especially interesting in the case of PD and RA connection is IL-17A, whose overproduction is mentioned as linked with chronic inflammation and autoimmune disease development." (PMID 39796056, 2024). "Th17 cells, known for their role in the inflammatory cascade of autoimmune diseases and as primary producers of IL-17 (including IL-17A and IL-17F), displayed a significant upregulation of gene sets implicated in IL-17 production." (PMID 39867884, 2024). "We identified a single temporal biomarker for type 1 diabetes, IL-17A/F, a cytokine that is associated with multiple other autoimmune diseases." (PMID 39078488, 2024). "IL-17A, a pro-inflammatory cytokine produced by Th17 cells, plays a critical role in inflammatory and autoimmune diseases and has been implicated in several conditions, including lamellar injury." (PMID 39330774, 2024).
autoimmune disease (continued). "The pain linked with autoimmune diseases, such as arthritis and psoriasis, is associated with IL-17A, which induces a fast increase in neuronal excitability, and implicates the involvement of this molecule in the evolution of these disease processes." (PMID 36833753, 2023). "PAR2 and IL-17A are associated with autoimmune diseases that lead to chronic pain, and PAR2 regulates T-helper (Th) cell activation and differentiation." (PMID 38139455, 2023). "IL-17A levels have been implicated in autoimmune disease pathogenesis and contribute to impaired lung function caused by respiratory viruses like RSV." (PMID 37795093, 2023). "In one case report, anti-IL-17A treatment was beneficial for preventing the development of an autoimmune disease in a patient, but at the same time, it caused the loss of an antitumor response in the same patient who also suffered from CRC." (PMID 38068860, 2023). "In humans, increased IL-17A level is associated with infections, antimicrobial immunity, chronic inflammatory diseases, obesity, and autoimmune diseases." (PMID 36835413, 2023). "Interleukin-17A (IL-17A) is a component of the microenvironment associated with some autoimmune diseases." (PMID 38007487, 2023). "T helper type 17 (TH17) cells, which produce interleukin-17A (IL-17A) and IL-17F, have been implicated in the pathogenesis of several autoimmune diseases." (PMID 37190070, 2023). "IL-17-producing T helper (Th17) cells, which are characterized by the production of their signature cytokine, IL-17A, are associated with various autoimmune diseases, including RA and multiple sclerosis." (PMID 36397156, 2022). "Considering the importance of IL17a producing γδT cells on the skin and other autoimmune diseases, it is crucial to elucidate the underlying molecular mechanism behind how Sgpl1 deficiency affects γδ17T cell subsets differently." (PMID 35769463, 2022). "At the same time, in many pathological processes, especially in the process of the chronic and continuous immune response, IL-17A can cause autoimmune diseases and damage tissue structures." (PMID 36119497, 2022). "IL-17A is a pro-inflammatory cytokine implicated in the pathogenesis of inflammatory and autoimmune diseases." (PMID 34682792, 2021). "Its human orthologs, IL-17A and IL-17F, are implicated in autoimmune disease, chronic asthma, chronic mucocutaneous candidiasis, rhinitis, and MS." (PMID 34281170, 2021). "Although IL-17A plays an important role during bacterial and fungal infections, when produced in excess it is implicated in the pathogenesis of autoimmune diseases." (PMID 34040613, 2021). "We want to emphasize that IL-17A is produced by T-helper 17 lymphocytes (Th-17 cells) and is mainly associated with autoimmune diseases." (PMID 34065135, 2021). "IL-17A is specifically produced by Th17 cells, which are closely associated with the pathogenesis of autoimmune disorders." (PMID 33919375, 2021). "Although IL-17A has been identified as the main mediator of inflammation associated with autoimmune disease, the pathways downstream of IL-17A binding to IL-17R are still not fully defined." (PMID 32582209, 2020). "In ankylosing spondylitis (AS), another autoimmune disease, IL-17A has been shown to contribute to pathogenic inflammation." (PMID 33132897, 2020). "Studies have shown that PCOS associated with low-grade chronic inflammation interleukin-17A (IL-17A) is one of the major members of pro-inflammatory cytokines, and is mainly involved in the development of inflammatory and autoimmune diseases." (PMID 32785222, 2020). "Genes encoding IL-17A and IL-17F are located on chromosome 6 (6p12), and polymorphisms in these genes were studied in various autoimmune diseases." (PMID 30961540, 2019). "Since Th17 cells can secrete IL-17A, and IL-17A is a pro-inflammatory cytokine that can cause tissue damage, this provides a negative factor in the long-term control of chronic inflammatory and autoimmune diseases." (PMID 30974919, 2019).
autoimmune disease (continued). "IL-17A is a cytokine mainly produced by Th17 cells and is strongly associated with a series of inflammatory conditions and autoimmune diseases." (PMID 31827384, 2019). "Our study reveals a critical pathogenic mechanism of GLK-induced IL-17A transcription in autoimmune diseases." (PMID 30214937, 2018). "IL-17A and IL-17F were initially associated with the pathogenesis of autoinflammatory and autoimmune disorders." (PMID 30364284, 2018). "Among them, IL-17A and IL-17F have been described to closely associate with development of autoimmune diseases via interactions with a receptor complex formed by IL-17 receptor A and C." (PMID 30304852, 2018). "Because IL-17A is a pro-inflammatory cytokine, its dysregulation is associated with various autoimmune disorders, such as type 1 diabetes, rheumatoid arthritis, and Sjögren’s syndrome." (PMID 28831064, 2017). "IL-17a plays a dual role in the antitumor immunity and is also a key player in the inflammation and tissue destruction associated with autoimmune disease." (PMID 29137294, 2017). "Th17 cells differentiate in response to IL-1β, IL-6, IL-23, and TNF-α; secrete IL-17A, IL-17F, and IL-21; and play a critical pathogenic role in T cell-mediated autoimmune diseases." (PMID 28458638, 2017). "Th17 cells, specifically implicated in autoimmune diseases including type 1 diabetes, can secrete IL-22 and IL-17A, which has been identified as a factor promoting the pro-inflammatory effect of IL-22." (PMID 26751709, 2016). "As for the relationships with susceptibility or progression of other autoimmune diseases the associations of the IL-17A rs2275913 variants with ulcerative colitis in Koreans and Japanese, but not for our Caucasian population, were described." (PMID 25387578, 2015). "Although IL-17A/F is typically associated with destructive tissue damage in autoimmune disease and pathogen infections, it is also involved in protective immunity." (PMID 26783383, 2015). "Interleukin 17A and its receptor play a pathogenic role in many inflammatory and autoimmune diseases." (PMID 24959203, 2014). "Th17 cells, a CD4 T helper subset characterized by the production of IL-17A, IL-17F, IL-21, and IL-22 cytokines, are implicated in the pathogenesis of many autoimmune diseases." (PMID 23505568, 2013). "Systemically, IL-17A and IL-17F have been reported to play a pathogenic role in certain autoimmune diseases, including multiple sclerosis and rheumatoid arthritis." (PMID 23956759, 2013). "Interleukin-17A (IL-17A), the cytokine tightly associated with various autoimmune diseases, was known to play protective or pathological roles in LPS and ConA-induced hepatitis." (PMID 24069246, 2013). "Because IL-17A and IL-17F are critical cytokines produced by Th17 cells and have been linked to numerous autoimmune diseases, we further investigated the role of TCF-1 in Th17 differentiation." (PMID 21935461, 2011). "Interleukin 17A and its receptor play a pathogenic role in many inflammatory and autoimmune diseases such as rheumatoid arthritis." (PMID 21909410, 2011). "We therefore propose IL-17A as a suitable target to combat bone loss in inflammatory arthritis and autoimmune diseases such as RA." (PMID 20167120, 2010). "Collectively our data demonstrate anti-IL-17A treatment as a selective therapeutic target for bone loss associated with autoimmune diseases." (PMID 20167120, 2010). "In the context of IL-17A-driven autoimmune diseases with associated vascular pathology, our findings suggest that anti-inflammatory therapies alone may not be sufficient to attenuate vascular impairment." (PMID 41750609, 2026). "Maintaining an appropriate balance of IL-17 is essential for immune homeostasis; however, dysregulated production—particularly of IL-17A—is associated with the pathogenesis of numerous inflammatory and autoimmune diseases." (PMID 41357230, 2025).
autoimmune disease (continued). "Specifically in MS, the species Collinsella, Prevotella, and Eggerthella may serve as a potential biomarker for autoimmune disorders, since they are associated with IL-17A production and chronic inflammation." (PMID 39203576, 2024). "Therefore, EBV induces a pro-autoimmune response causing an elevation in systemic and tissue IL-17A levels, thus acting as a risk factor for the development of autoimmune diseases." (PMID 38675965, 2024). "Moreover, IL-17A is implicated in the pathogenesis of some autoimmune diseases, including ankylosing spondylitis for which an IL-17A inhibitor (secukinumab) is approved." (PMID 37483633, 2023). "However, IL-17A overproduction has been associated with chronic inflammatory disorders, autoimmune diseases, and cancers." (PMID 38068860, 2023). "The rs3819025 SNP of IL-17A was reported to be associated with autoimmune disease." (PMID 38139455, 2023). "Th17 and IL-17A are also associated with the severity and progression of autoimmune diseases." (PMID 38139455, 2023). "IL‐17A has been linked to the pathogenesis of autoimmune diseases." (PMID 37249293, 2023). "IL-17A has been implicated in the pathogenesis of many autoimmune diseases, especially in MS." (PMID 36857006, 2023). "Studies have shown that irAEs caused by ICIs have a pathogenesis similar to that of autoimmune disorders, and hyperreactivity of Th17 cells and proinflammatory cytokines such as IL-17A, IL-21 and IL-22 have prominent roles in the pathogenesis of many autoimmune diseases." (PMID 36793048, 2023). "Moreover, IFN-γ+IL-17A+ Th17 cells usually exerting pathogenic roles in many autoimmune diseases also exist in the SGs of SjS patients." (PMID 35681462, 2022). "Both IL-17A and IL-17F can generate homodimers or heterodimers and bind to heterodimeric IL-17RA and IL-17RC complexes, thereby activating downstream signaling transduction for host defense, autoimmune disease, or inflammation associated biological effects." (PMID 36274974, 2022). "IL-17A and its signaling are significant aspects of host defense against certain fungal and bacterial infections, and it is an important pathogenic factor in inflammatory and autoimmune diseases." (PMID 35955688, 2022). "Previous studies showed that IL-23/Th17 pathway and increased expression of IL-17A as well as IL-17A gene polymorphism have been associated with various autoimmune diseases, such as primary biliary cirrhosis, inflammatory bowel disease, rheumatoid arthritis and ulcerative colitis." (PMID 34446083, 2021). "Th17 cells and IL-17 are involved in host defenses by way of immunothrombosis, and promote the removal of pathogenic microorganisms, but too much IL-17A is fatal for the host, and can lead to a variety of inflammatory or autoimmune diseases." (PMID 34568080, 2021). "In addition, it has been demonstrated that the substitution of the G by an A allele in the IL17A rs2275913 gene promoter was significantly associated with autoimmune diseases and cancer." (PMID 32193469, 2020). "Finally, high levels of IL-17A have been implicated with tissular infiltrates composed primarily of CD8+ T-lymphocytes in autoimmune diseases, including ILD in idiopathic inflammatory myopathies, and particularly with severe complications of ASSD." (PMID 32384594, 2020). "Although IL-17 signaling confers protection against extracellular pathogens in the host, the IL-17 family of cytokines plays a crucial role in the inflammatory pathology of autoimmune diseases, with a close correlation with the subset of T helper 17 (Th17) cells and their hallmark cytokine, IL-17A." (PMID 32382313, 2020). "IL-17A is linked to the pathogenesis of several inflammatory and autoimmune diseases including respiratory disorders such asthma where it activates MAPK and JAK/STAT signaling in airway smooth cells, leading to eosinophil recruitment and promotion of airway inflammation." (PMID 31791392, 2019).
autoimmune disease (continued). "IL-17A is associated with the development of various arthritic, allergic, and autoimmune disorders." (PMID 31531179, 2019). "IL-17A, commonly referred to as IL-17, is involved in normal physiological processes and is also a leading pathogenic cytokine in a wide range of pathologic conditions, including cancer and autoimmune disorders, due to its strong proinflammatory effects." (PMID 28210632, 2017). "IL-17A is an important cytokine implicated in the pathogenesis of autoimmune disease." (PMID 27266510, 2016). "The decreased levels of mRNAs encoding IFN-γ and IL-17A resulting from Gβγ inhibition could have applications for autoimmune diseases." (PMID 27095999, 2015). "IL-17A and IL-17F are primarily produced by a subset of T cells called Th17 and are highly homologous, which have been linked to cytokine and chemokine production in various inflammatory and/or autoimmune diseases, such as RA." (PMID 26252209, 2015). "The IL17A 197AA genotype was associated with tumorigenesis susceptibility as in gastric cancer, breast cancer, and cervical cancer, as well as autoimmunity diseases such as ulcerative colitis and rheumatoid arthritis." (PMID 26339129, 2015). "IL-22 and IL-17A are implicated in the pathogenesis of autoimmune diseases." (PMID 24404171, 2014). "Recently, IL-17 (also known as IL-17A) is considered the signature cytokine in the Th17 cell population and has been implicated as having a role in the pathogenesis of numerous autoimmune diseases, including RA." (PMID 24742125, 2014). "IL-17 (also called IL-17A) is a hallmark pro-inflammatory cytokine of Th17 cells that plays an important role in several human autoimmune diseases and microbial infection disease of many animals, and it may play a role in Cryptosporidium infection." (PMID 24886047, 2014). "Although IL-17A (commonly referred to as IL-17) has been implicated in the pathogenesis of central nervous system (CNS) autoimmune disease, its role during CNS bacterial infections remains unclear." (PMID 22704602, 2012). "The dual nature of IL-17A to be either pathogenic or protective has been reported, and its specific function may depend on the stage of different autoimmune diseases." (PMID 21686325, 2011). "The IL-23/IL-17A axis has recently been implicated in joint pathology and autoimmune diseases." (PMID 20167120, 2010). "However, excessive IL-17A production has been linked to numerous autoimmune diseases." (PMID 34752458, 2021). "IL-17A, the most studied cytokine of this family, is a pro-inflammatory cytokine critical in the defense against microbial infections; it is involved in different conditions associated with systemic inflammation, including autoimmune diseases, metabolic disorders and malignancy." (PMID 31803028, 2019). "Both IL-17A/F and their receptors genes exhibit functional polymorphisms that may alter qualitatively and/or quantitatively their expressions and hence influence predisposition to autoimmune diseases." (PMID 29584788, 2018). "IL-17F, in conjunction with IL-17A, contributes significantly to the onset and progression of various chronic inflammatory and autoimmune diseases." (PMID 40536951, 2026). "This is of interest as IL-17A is one factor linking several autoimmune diseases with cardiovascular comorbidity." (PMID 41750609, 2026). "In autoimmune diseases, IL-17A is mainly produced by pathological Th 17 cells, whereas in urinary tract infections it is synthesized by Tγδ lymphocytes, which can recognize bacterial ligands independently of MHC restriction." (PMID 40093533, 2025). "IL-17A is a well-known pro-inflammatory cytokine for several autoimmune diseases, and gaining attention in the context of obesity." (PMID 40529363, 2025). "IL-17A is a pro-inflammatory cytokine with prominent roles in allergic and autoimmune diseases, such as multiple sclerosis, rheumatoid arthritis, psoriasis, asthma, Crohn’s disease, and cancers." (PMID 40632810, 2025).